KNSTRN (kinetochore localized astrin (SPAG5) binding protein)
Diseases named in the same sentence as KNSTRN in open-access papers (continued):
Sharing a sentence is not in itself a finding about the gene and the disease.
KNSTRN also shares sentences with these, for which no sentence is quoted: skin cancer (4 papers); infection (2); lung squamous cell carcinoma (2); triple-negative breast carcinoma (2); astrocytoma (1); bladder urothelial carcinoma (1); breast invasive carcinoma (1); cervical squamous cell carcinoma (1); cholangiocarcinoma (1); colon adenocarcinoma (1); cutaneous melanoma (1); endocervical adenocarcinoma (1); head and neck squamous cell carcinoma (1); Immunodeficiency (1); infiltrating ductal carcinomas (1); mucosal melanoma (1); non-small cell lung carcinoma (1); osteosarcoma (1); prostate adenocarcinoma (1); rectal adenocarcinoma (1); renal cell carcinoma (1); squamous cell carcinoma (1); stomach adenocarcinoma (1); testicular germ cell tumor (1); uterine corpus endometrial carcinoma (1); uveal melanoma (1).